EIF2AK1 (eukaryotic translation initiation factor 2 alpha kinase 1)
Description:
Metabolic-stress sensing protein kinase that phosphorylates the alpha subunit of eukaryotic translation initiation factor 2 (EIF2S1/eIF-2-alpha) in response to various stress conditions. Key activator of the integrated stress response (ISR) required for adaptation to various stress, such as heme deficiency, oxidative stress, osmotic shock, mitochondrial dysfunction and heat shock. EIF2S1/eIF-2-alpha phosphorylation in response to stress converts EIF2S1/eIF-2-alpha in a global protein synthesis inhibitor, leading to a global attenuation of cap-dependent translation, while concomitantly initiating the preferential translation of ISR-specific mRNAs, such as the transcriptional activator ATF4, and hence allowing ATF4-mediated reprogramming. Acts as a key sensor of heme-deficiency: in normal conditions, binds hemin via a cysteine thiolate and histidine nitrogenous coordination, leading to inhibit the protein kinase activity (By similarity). This binding occurs with moderate affinity, allowing it to sense the heme concentration within the cell: heme depletion relieves inhibition and stimulates kinase activity, activating the ISR (By similarity). Thanks to this unique heme-sensing capacity, plays a crucial role to shut off protein synthesis during acute heme-deficient conditions (By similarity). In red blood cells (RBCs), controls hemoglobin synthesis ensuring a coordinated regulation of the synthesis of its heme and globin moieties (By similarity). It thereby plays an essential protective role for RBC survival in anemias of iron deficiency (By similarity). Iron deficiency also triggers activation by full-length DELE1. Also activates the ISR in response to mitochondrial dysfunction: HRI/EIF2AK1 protein kinase activity is activated upon binding to the processed form of DELE1 (S-DELE1), thereby promoting the ATF4-mediated reprogramming. Also acts as an activator of mitophagy in response to mitochondrial damage: catalyzes phosphorylation of eIF-2-alpha (EIF2S1) following activation by S-DELE1, thereby promoting mitochondrial localization of EIF2S1, triggering PRKN-independent mitophagy.
Synonyms: HCR; hHRI; HRI; KIAA1369
Tractability: Small molecule: a high-quality ligand is known; it belongs to a druggable protein family. PROTAC: UniProt records ubiquitination sites on it; ubiquitination databases record sites on it; a small molecule that binds it is known.
Target class: Enzyme; Protein Kinase; Other protein kinase PEK family; Other protein kinase HRI; Other protein kinase group; Kinase
Chemical probes: BTdCPU
Gene: Protein-coding gene on chromosome 7 (6,022,247 to 6,059,231, reverse strand). Ensembl gene ENSG00000086232.
Subcellular location (Human Protein Atlas): Nucleoplasm; Cytosol
Pathways (Reactome):
Cellular responses to stimuli: Cellular response to mitochondrial stress; Response of EIF2AK1 (HRI) to heme deficiency
Gene Ontology:
Molecular function: eukaryotic translation initiation factor 2alpha kinase activity; protein binding; protein serine kinase activity; heme binding; protein homodimerization activity; ATP binding; protein kinase activity; protein serine/threonine kinase activity
Biological process: HRI-mediated signaling; integrated stress response signaling; positive regulation of mitophagy; protein localization to mitochondrion; response to iron ion starvation; negative regulation of hemoglobin biosynthetic process; negative regulation of translational initiation by iron; protein autophosphorylation; regulation of translational initiation; negative regulation of cell population proliferation; response to stress
Cellular component: cytosol; nucleoplasm; cytoplasm; nucleus
Genetic constraint (gnomAD): Loss-of-function variants: 47 observed, 67.8 expected, observed/expected ratio (o/e) 0.69, 90% interval 0.55 to 0.88. The upper end of that interval is the gene's LOEUF score, 0.88, which puts it in group 3 of 6, group 1 being the genes least tolerant of losing a copy. Missense variants: 740 observed, 713.36 expected, observed/expected ratio (o/e) 1.04, 90% interval 0.98 to 1.1. Synonymous variants: 299 observed, 275.65 expected, observed/expected ratio (o/e) 1.08, 90% interval 0.99 to 1.19.
Homologues: Orthologues: chimpanzee EIF2AK1 (99% identical), chimpanzee EIF2AK1 (97% identical), macaque EIF2AK1 (94% identical), dog EIF2AK1 (84% identical), pig EIF2AK1 (82% identical), mouse Eif2ak1 (82% identical), rat Eif2ak1 (81% identical), rabbit EIF2AK1 (80% identical), guinea pig EIF2AK1 (76% identical), tropical clawed frog eif2ak1 (45% identical), zebrafish eif2ak1 (41% identical), Drosophila melanogaster Wee1 (14% identical). Paralogues in human: EIF2AK4 (25% identical), EIF2AK3 (24% identical), EIF2AK2 (18% identical), WEE1 (16% identical), WEE2 (14% identical), PKMYT1 (13% identical), STK35 (12% identical), PDIK1L (10% identical).
Diseases named in the same sentence as EIF2AK1 in open-access papers:
EIF2AK1 is named in the same sentence as 37 diseases in open-access papers, as found by Europe PMC text mining. Sharing a sentence is not in itself a finding about the gene and the disease. The quoted sentences say what the papers report.
viral infection (37 papers, 2013 to 2026). "In addition to GCN2, there are three other mammalian eIF2α kinases: PERK (EIF2AK3/PEK), PKR (EIF2AK2) and HRI (EIF2AK1), which are activated by endoplasmic reticulum (ER) stress, viral infection, and heme deprivation in reticulocyte cells, respectively." (PMID 31194856, 2019). "The ISR is activated in response to many different types of cellular stress (including amino acid starvation and viral infection) and is mediated by four different cellular kinases, EIF2AK1 (HRI), EIF2AK2 (PKR), EIF2AK3 (PERK) and EIF2AK4 (GCN2)." (PMID 39951426, 2025). "Heme-regulated inhibitor (HRI, EIF2AK1) and protein kinase R (PKR, EIF2AK2) are activated in erythroid cells by heme deprivation and viral infections, respectively." (PMID 27085088, 2016).
glioma (3 papers, 2013 to 2022). A benign or malignant brain and spinal cord tumor that arises from glial cells (astrocytes, oligodendrocytes, ependymal cells). "EIF2AK1 was identified as a target gene of some miRNAs (such as miR-129, −145, −155), which have been shown to function in glioma cell growth." (PMID 35635065, 2022). "Nine novel functional miRNAs (hsa-miR-129, -136, -145, -155, -181b, -342-5p, -342-3p, -376a/b) in GBM cell lines were validated for their importance in glioma cell growth, and similar effects for six target genes (ROCK1, RHOA, MET, CSF1R, EIF2AK1, FGF7) of these miRNAs were shown functionally." (PMID 23577178, 2013).
ovarian carcinoma (2 papers, 2023 to 2025). A malignant neoplasm originating from the surface ovarian epithelium. "Moreover, mifepristone activates cytotoxic effects through the eIF2AK1-mediated signal transduction pathway, promoting the drug synergies in ovarian cancer therapy." (PMID 37509133, 2023).
prostate carcinoma (2 papers, 2012 to 2015). A carcinoma that arises from epithelial cells of the prostate gland. "Fusion gene EIF2AK1-ATR is oncogenic and overexpressed in androgen-independent prostate cancer cells." (PMID 26517092, 2015).
breast carcinoma (1 paper, 2017). "Although no information links this gene to breast cancer, it has been demonstrated in a mouse xenograft model of human breast cancer that an activator of EIF2AK1 protein was associated with tumor growth inhibition compared with vehicle." (PMID 29108258, 2017).
Cockayne syndrome-B (1 paper, 2014). "TFII-I interacted with genes encoding for the heme-regulated eIF2α kinase HRI (EIF2AK1), the Cockayne syndrome-B (CS-B or ERCC6), heterochromatin protein 1 beta (Hp1 beta, CBX1) and TF ATF3." (PMID 24875474, 2014).
infection (7 papers, 2013 to 2025). The state of being infected such as from the introduction of a foreign agent such as serum, vaccine, antigenic substance or organism. "Having excluded a role for GCN2, we next asked whether the ISR kinases (PKR)-like endoplasmic reticulum kinase (PERK), Protein kinase R (PKR), or eukaryotic translation initiation factor 2-alpha kinase 1 (HRI) mediated ISR activation during infection." (PMID 40811546, 2025). "RT-qPCR did not reveal significant differences in the amount of TMEV RNA as well as Ifnb1, Isg15, Eif2ak1 (PKR), Tnfa, Il1a, Il1b, Il6, Il10, Il12 (p40) and Ifng transcript numbers in the brain of Asc−/− and Casp1−/− mice and their respective wild type littermates at 4 days after TMEV infection." (PMID 37414913, 2023).
tumor (7 papers, 2012 to 2026). "Two of these genes (EIF2AK1 and AIMP2) have tumor-suppressing functions." (PMID 22585707, 2012).
EIF2AK1 also shares sentences with these, for which no sentence is quoted: cancer (8 papers); Iron deficiency (3); anemia (2); Alzheimer disease (1); Ataxia (1); atherosclerosis (1); bacterial infection (1); breast tumors (1); cardiac hypertrophy (1); carnitine deficiency (1); cervical cancer (1); colon cancer (1); coronary artery disease (1); dementia (1); gastric cancer (1); hematologic diseases (1); neuroblastoma (1); neurodegenerative disease (1); osteosarcoma (1); pancreatic cancer (1); pulmonary fibrosis (1); pulmonary hypertension (1); reovirus infection (1); rheumatoid arthritis (1); serous carcinomas (1); Splenomegaly (1); thalassemia (1); ZIKV infection (1); α-synucleinopathies (1).